RHOA (ras homolog family member A)
Diseases named in the same sentence as RHOA in open-access papers (continued):
Sharing a sentence is not in itself a finding about the gene and the disease.
breast carcinoma (continued). "Also, while it is established that RhoC is relevant to breast cancer survival (via cell death inhibition) and progression (via the promotion of proliferation, invasion, and metastasis), data accumulated so far only reveals the relevance of RhoA to breast cancer cell progression." (PMID 40214422, 2025). "A study of human breast cancer showed that CD74 interacted with CD44 to promote tumorigenesis and metastasis of MDA-MB-231 cell through the regulation of RHOA." (PMID 38874510, 2024). "In breast cancer, high expression of miR‐182 suppresses the MIM (Missing in Metastasis) and triggers Ras homolog family member A (Rho A), which induces metastasis." (PMID 39617640, 2024). "MiR-31 has been shown to target key genes of cell migration such as RHOA and ITGA5 and attenuated breast cancer cell invasion." (PMID 37833432, 2023). "Previous research showed that EphA2 and ErbB2 can form a complex, resulting in increased activation of the RhoA GTPase and MAPK pathways in breast cancer cells." (PMID 36880347, 2023). "KLF14 suppressed breast cancer cell invasion and M2 macrophage polarization through modulating SOCS3/RhoA/Rock/STAT3 signaling." (PMID 38143751, 2023). "We therefore determined, in subsequent analysis, the effects of selected genes from our SB screens on growth and migration of established human breast cancer cell lines with known RB status, MET and RhoA signaling." (PMID 37463901, 2023). "Label-free quantitative proteomic analysis of the proteome isolated from the MCF-7 breast cancer cell line, treated with 1 μM of doxorubicin, identified RAC1, CDC42, and RHOA GTPases that were inactivated by the ARHGAP1 protein." (PMID 37511111, 2023). "They demonstrated increased activity of GTP-bound RHOC and RHOA in tumors compared to natural tissues, and showed that RHO expression and RHO activation are two independent parameters in the different types of breast cancer." (PMID 35933373, 2022). "GBP-2 inhibits breast cancer cell migration by inhibiting the activation of Rac1, while promoting the activation of CDC42 and RhoA." (PMID 35681772, 2022). "Herein, we established novel angiogenic signaling pathway that overexpression of YAP in breast cancer cells activated YAP in endothelial cells resulted in migration and tube formation through G13/RhoA and VE-cadherin/PI3K/Akt pathway." (PMID 36226237, 2022). "miR-31 decelerates breast cancer metastasis by targeting genes such as integrin α5 (ITGA5), radixin (RDX), and Ras homolog family member A (RhoA)." (PMID 35805066, 2022). "DIAPH3 is decreased in breast cancer tissues, and DIAPH3 overexpression inhibits cell migration and invasion of triple-negative breast cancer by inhibiting RhoA-GTP expression." (PMID 35379791, 2022). "In breast cancer, it has been demonstrated that the polarisation of M2 macrophage was modulated by KLF14 via SOCS3/RhoA/ROCK signalling pathway, thereby suppressing tumour growth." (PMID 36178087, 2022). "For example, SDCBP was found to modulate RhoA and Cdc42 expression via TGF-β1, which induced EMT and promoted breast cancer metastasis." (PMID 35155233, 2022). "NGF stimulates the invasion of breast cancer MDA-MB-231 cells as a result of the binding of CD44 with the TrkA receptor and the activation of the p115RhoGEF/RhoA/ROCK1 cascade." (PMID 35956937, 2022). "High levels of Nrf2 are associated with tumorigenesis and poor prognosis, and it promotes RhoA expression by interacting with and silencing the ERR1 gene, allowing breast cancer cells to proliferate and metastasize." (PMID 35571115, 2022). "In breast cancer cells, c-Myc has been found to heterodimerize with the transcription factor Max and to bind to the E-box motif CACGTG in the RHOA promoter in cooperation with the coactivator complex Skp2-Miz1-p300, hereby activating RHOA transcription." (PMID 35563826, 2022).
breast carcinoma (continued). "After bacteria invaded breast cancer cells, RhoA-ROCK signaling pathway can be activated to reorganize the cytoskeleton and help breast cancer cells resist the pressure from blood vessels and avoid damage during metastasis." (PMID 36033476, 2022). "Collectively, these results suggested the existence of a signal transduction from RKIP to breast cancer invasion/metastasis through Erk2, GEFH1, RhoA and E-cad." (PMID 34465801, 2021). "LOX, MMP2, MMP3, MMP9, RHOA, VIM gene panel expression monitoring was considered because they are correlated with a more aggressive and invasive phenotype in breast cancer cells." (PMID 33543395, 2021). "This study demonstrates that the RhoA or RhoC/YAP pathway accelerated tumor metastasis via increased expression of RHAMM and CXCR4 in melanoma and breast cancer cells." (PMID 33406809, 2021). "The top three genes for breast cancer tissues and cell lines were SF1 + TRA2B + THRAP3 and THRAP3 + RHOA + QRICH1, respectively, and therefore a total of 5 RGs (SF1, TRA2B, THRAP3, RHOA, QRICH1) should be considered." (PMID 34895237, 2021). "In the breast cancer cell line group, THRAP3, RHOA, and QRICH1 were the three most stably expressed genes, while B2M, ACTB, and TUBA1A were the least stably expressed genes." (PMID 34895237, 2021). "In metastatic breast cancer cells, PI3K, Akt, mTOR, and RhoA were demonstrated to be responsible for migration regulation by CERK." (PMID 33430896, 2021). "In the breast cancer cell group THRAP3, RHOA, and QRICH1 were the top three stably expressed genes, while B2M, TUBA1A, and ACTB were the least stably expressed genes." (PMID 34895237, 2021). "In summary, the present study identified a physiological mechanism where RKIP suppresses breast cancer lung metastasis through Erk, GEFH1, RhoA, and E-cad." (PMID 34465801, 2021). "According to the ΔCt method, TRA2B, RHOA, and THRAP3 were the most stably expressed genes, while DNAJC8, GAPDH, and B2M were the least stable genes in the breast cancer tissue group, which was consistent with the analysis according to NormFinder." (PMID 34895237, 2021). "The CD99 molecule has previously been linked to Rho GTPase activity, actin dynamics and growth factor signalling in breast cancer; EGFR stimulates RhoA and Rac1 activity and actin reorganization, and these pathways are antagonised by CD99-mediated signalling." (PMID 34374417, 2021). "Our results indicated that SF1, TRA2B, and THRAP3 were the top 3 stably expressed RGs in breast cancer tissues and that THRAP3, RHOA, and QRICH1 were the top 3 stably expressed RGs in breast cancer cell lines." (PMID 34895237, 2021). "For all breast cancer tissue and cell line samples, THRAP3, RHOA, QRICH1 were the most stably expressed genes, and TUBA1A, B2M, ACTB were the least stably expressed RGs." (PMID 34895237, 2021). "There was a high correlation (R2 from 0.815 to 0.979 in breast cancer tissues, and R2 from 0.927 to 0.995 in breast cancer cell lines) between stable RGs and SF1 + TRA2B + THRAP3 + RHOA + QRICH1." (PMID 34895237, 2021). "There was also a moderate-to-high correlation (R2 from 0.621 to 0.709 in breast cancer tissues, and R2 from 0.600 to 0.916 in breast cancer cell lines) between unstable RGs and SF1 + TRA2B + THRAP3 + RHOA + QRICH1." (PMID 34895237, 2021). "In the breast cancer tissue group, TRA2B, RHOA, and THRAP3 were the most stable genes, and DNAJC8, GAPDH, and B2M were the most unstable genes." (PMID 34895237, 2021). "In the case of studies including both breast cancer tissue and cell line research, the THRAP3 + RHOA + QRICH1 combination would be optimal." (PMID 34895237, 2021). "EMAT clusters displayed distinct expression profiles for CDH1, VIM, RHOA, and JUP, well-accepted biomarkers of epithelial (E), mesenchymal (M), amoeboid (A), and collective cell migration in breast cancer, respectively." (PMID 32641077, 2020).
breast carcinoma (continued). "Rhosin inhibits the interaction of RhoA with multiple RhoGEFs, including LARG, Dbl, p115RhoGEF, and PDZ-RhoGEF, and suppresses the invasiveness of breast cancer cells." (PMID 32392742, 2020). "Tan and colleagues showed that TRIM59 stabilizes the apoptosis-related protein PDCD10 by inhibiting its ubiquitination and subsequent P62-selective autophagic degradation; in turn, this promoted RhoA and ROCK1 activation and metastasis of breast cancer cells." (PMID 33194618, 2020). "In breast cancer, GPRC5A has been reported to be downregulated and was identified to act as a tumor suppressor by RhoA/C and EGFR related signaling pathway." (PMID 33680947, 2020). "Aggressive and mesenchymal-transformed breast cancer cells show high expression levels of Rho GTPase activating protein 29 (ARHGAP29), a negative regulator of RhoA." (PMID 33291460, 2020). "WDR1 enhances the effect of MRTF-A-induced breast cancer cell migration by promoting the expression of EMT markers and migration markers by RhoA-MRTF." (PMID 33194737, 2020). "The knockdown of RhoA by siRNA inhibits the growth and angiogenesis of xenografted MDA-MB-231 breast cancer cell lines." (PMID 32392742, 2020). "Lastly, transient degradation of RhoA and RhoC proteins by targeted siRNAs significantly reduced MDA-MB-231 TNBC cell growth in vitro and in mouse models of breast cancer." (PMID 32992837, 2020). "In support of this, Shang and colleagues demonstrated that direct inhibition of RhoA by their drug, Rhosin, inhibited cell growth of MCF-7 breast cancer cells." (PMID 32992837, 2020). "It should be noted that some genes highly related with breast cancer rank at top but are missed by the NCG4.0 such as the CREBBP, RHOA, HDAC1, ATM and MYC." (PMID 31088372, 2019). "We found that specific genes such as CBL, RHOA, EP300, RAC1, CDK1, and CDH1 are involved in the migration and invasion of breast cancer." (PMID 30930932, 2019). "S1PR1 regulated RhoA activation to accelerate VE-cadherin phosphorylation (Y731), leading to increased EDV and reduced VM in human breast cancer cells." (PMID 30814488, 2019). "The results show that S1PR1 regulated RhoA activation to accelerate VE-cadherin phosphorylation (Y731), leading to increased EDV and reduced VM in breast cancer." (PMID 30814488, 2019). "GGPPS inhibition can reduce RhoA geranylgeranylation and membrane localization through GGPP depletion, and thus inhibit breast cancer cell migration." (PMID 29377583, 2018). "The overexpression of Nrf2 was identified in a variety of tumors, and, especially, it was found that Nrf2 promoted cell proliferation and metastasis by increasing RhoA protein stability and expression in MCF-7 and MDA-MB-231 breast cancer cells." (PMID 28758930, 2017). "It binds to the surface of RhoA by Trp58, suppresses interaction of the LARG GEF-stimulated and blocks RhoA-mediated cytoskeletal activity and invasiveness of breast cancer cells." (PMID 27304967, 2016). "WNT-5A induces RhoA activation via DVL and Daam1 in breast cancer cells or via PI3K/AKT signaling in gastric cancer cells." (PMID 26514730, 2016). "Since the Rho family GTPases, RhoA and Cdc42, are known modulators of the actin cytoskeleton and play a vital role in EMT and metastasis in breast cancer, we assessed the activity of these GTPases following MDA-9 modulation." (PMID 27863394, 2016). "We demonstrated that NRF2, whose high expression correlates with tumor aggressiveness and poor prognosis, induced RhoA expression by its binding to and silence ERR1 gene and promoted breast cancer cell proliferation and metastasis." (PMID 27713154, 2016). "In summary, we demonstrate that CD74 promotes breast cancer cell metastasis, that CD74 and CD44 coordinately upregulate CFL1 phosphorylation through RHOA pathway, and that the repression of CD74 expression suppresses xenograft growth in vivo." (PMID 27626171, 2016).
breast carcinoma (continued). "In conclusion, our findings indicate that RhoA/ROCK signaling, which leads to cytoskeletal rearrangement, plays an important role in the phenotype of breast cancer cells and the disrupted tissue architecture in breast cancer." (PMID 27203208, 2016). "Furthermore, Compound 1 could not promote cell proliferation in RhoA silenced MDA-MB-231 and MCF7 cells compared with cells transfected with siCtrl alone, indicating that RhoA is able to reverse the inhibitory effect on cell proliferation by NRF2 downregulation in breast cancer cells." (PMID 27713154, 2016). "The high basal levels of RhoA-GTP observed here in cervical adenocarcinoma HeLa cells are similar to those reported for other cancer cell lines, including the breast cancer cell line MDA-MB-231, and also in colorectal cancer cell lines and tumor samples." (PMID 26649141, 2016). "mRNA and protein expression of ROCK1, ROCK2 and RhoA are increased in the tissue of breast cancer patients; however, only the increased levels of ROCK1 and RhoA correlate with poor patient prognosis." (PMID 27203208, 2016). "We examined the expression level of RhoA in COS-7 cells and various breast cancer cells including BT-20, MCF-7, MDA-MB-453, and SKBR-3 cells." (PMID 26816343, 2016). "Only recently was NC found to inhibit the phosphorylation of c-Src, FAK, MAPKs, and inhibit the activation of RhoA, Rac1, and AP-1 transcriptional activity induced by PDGF in breast cancer cells." (PMID 27821837, 2016). "In breast cancer cells, CD44 has been shown to stimulate the guanine exchange activity of p115RhoGEF leading to activation of RhoA, a GTPase involved in cytoskeletal organization and adhesion." (PMID 25886367, 2015). "We demonstrated that the migration and adhesion sequences of breast cancer cells, induced by SDF-1α gradients, involves successively the activation and inactivation of RhoA and an increased expression of Rac1 through the gradient." (PMID 26231656, 2015). "In breast cancer, Met-F-AEA leads to the inhibition of the focal adhesion kinase (FAK) and RhoA-ROCK pathways." (PMID 25115386, 2014). "We demonstrated that RhoA and RhoC are PFI targets that are essential for the invasive potential of breast cancer cells." (PMID 24587105, 2014). "miR-31, a well-known anti-metastatic miRNA in breast cancer, was first shown to inhibit breast cancer metastasis both in vitro and in vivo through the targeting of integrin-α5 (ITGA5), radixin (RDX) and RhoA and later through targeting of WAVE3." (PMID 25927669, 2014). "This work was conducted to analyze the implication of Rac3 in the aggressiveness of two breast cancer cell lines, MDA-MB-231 and MCF-7: both express Rac3, but MDA-MB-231 expresses more activated RhoA." (PMID 23388133, 2013). "More specifically, in breast cancer cells, miR-155 has been shown to facilitate TGF-β-induced EMT by targeting RhoA." (PMID 22752005, 2012). "STARD13 (DLC2), a tumor suppressor protein, has growth-suppressive and anti-metastatic effects on breast cancer cell lines MCF-7/ADR and can inhibit the activity of RhoA." (PMID 22693547, 2012). "In contrast, miR-155 is overexpressed in breast cancer by the TGF-β/Smad4 pathway and mediates TGF-β-induced EMT by directly targeting RhoA in NMuMG cells." (PMID 22200848, 2012). "ER-dependent PI3K activation results in the activation of the RhoA/ROCK-2 cascade and through this manner it increases ezrin activity in breast cancer cells." (PMID 21818323, 2011). "Perhaps a balance is obtained between the free Etk/Bmx-PH domain in activating RhoA and the PAR1-C-tail immobilized Etk/Bmx-PH domain, in the delicate control of cytokeletal reorganization and actin stress fiber formation during breast cancer progression." (PMID 20559570, 2010). "Since RhoA is engaged in cytoskeleton reorganisation to promote cancer invasion, we studied the effect of ZOL on the morphology of MDA-MB-231 breast cancer cells." (PMID 12771933, 2003).
breast carcinoma (continued). "Similarly, RhoA and RhoC knockdown by siRNA was also reported to reduce invasion, motility, and monolayer growth rate in SUM149 and MDA-MB-231 breast cancer cells." (PMID 40214422, 2025). "The RBP4/RhoA/Rock1 axis has been found to regulate the proliferation, migration, and invasion of ovarian cancer cells, while NRG2 was identified as a prognostic marker for GC and breast cancer and LBP as a prognostic marker for GC." (PMID 40406134, 2025). "In addition to NSCLC, depleted levels of RAC1, CDC42, and RHOA were also observed in several other cell lines, including lung cancer (A549 and NCI-H1299) and breast cancer (MDA-MB-468 and MDA-MB-231), following PCAIs treatment." (PMID 38540084, 2024). "Furthermore, both breast cancer cell lines exhibited significant reductions in the levels of KRAS, RHOA, RAC1, and CDC42 proteins of 49, 40, 50, and 48%, respectively in MDA-MB-468 cells." (PMID 36961909, 2023). "A study using a breast cancer cell line suggests that TNS3 silencing activates the Rho-GAP function of DLC1 through releasing an autoinhibitory effect, and thereby elevating the level of RhoA-GTP." (PMID 37668682, 2023). "To assess whether Vangl regulates the cytoskeleton in leader cells, we employed time-lapse microscopy of collectively migrating breast cancer cells depleted of Vangl2 and stably expressing FRET biosensors for cytoskeletal regulators Rac1 and RhoA." (PMID 37147680, 2023). "Work in breast cancer cells extended this work by showing that GBP-2 inhibits cell migration and invadosome formation, accompanied by inhibition of Rac1 and activation of Cdc42 and RhoA." (PMID 35681772, 2022). "The miR-125b/STARD13 regulatory axis has been confirmed in our previous studies, and we indicate that STARD13 3’UTR suppresses breast cancer stemness by inhibiting YAP/TAZ activity through co-regulating Hippo and RhoA (Ras homolog gene family, member A) signaling." (PMID 35057866, 2022). "Moreover, we confirmed that 4T1 cells, a highly metastatic mouse breast cancer cell line, expressed total and GTP-form RhoA and RhoC." (PMID 33406809, 2021). "In breast cancer cell lines, when the optimal RG combinations SF1 + TRA2B + THRAP3 + RHOA + QRICH1, SF1 + TRA2B + THRAP3, or THRAP3 + RHOA + QRICH1 were used for normalization, the expression of FAAH was highest in MCF-7 cells, followed by MCF-10A cells, and was least in MDA-MB-231 cells." (PMID 34895237, 2021). "In the breast cancer cell lines, THRAP3, RHOA, and QRICH1 were the most stably expressed RGs." (PMID 34895237, 2021). "Likewise, the same effect was seen after specific knockdown of RHOA, ROCK1 and ROCK2 by siRNA in all three ROR2-overexpressing breast cancer cell lines." (PMID 34911552, 2021). "Specially, curcumin reduces LPA activated RhoA and ROCK in MCF7 breast cancer cells." (PMID 33923651, 2021). "Also, the phosphorylation of RhoA, ROCK1 and LIMK1 in breast cancer cells is positively regulated by MEX3A." (PMID 34486491, 2021). "While there was an effect on the GTPase activity of RhoA in breast cancer cells with altered RKIP expression, we did not observe any difference in the RhoA transcripts as measured by qt-RT-PCR or DNA microarray analysis (data not shown)." (PMID 34465801, 2021). "Therefore, we next applied our imaging and analysis strategy to explore the potential for fragmented mitochondria in breast cancer cells that lack either the Rho-like family of Rho-GTPases RhoA or RhoC via CRISPR/Cas9 knockout (WT, RhoA KO, RhoC KO)." (PMID 32472013, 2020). "We further demonstrated that ALOX5 is important for breast cancer biological activities with the predominant roles in growth and migration, likely through RhoA, focal adhesion, and PI3K/Akt/mTOR signaling but not epithelial mesenchymal transition (EMT)." (PMID 33224971, 2020).